RNU6-491P (RNA, U6 small nuclear 491, pseudogene)
Gene: Small nuclear RNA gene on chromosome 12 (14,250,232 to 14,250,341, reverse strand). Ensembl gene ENSG00000251908.
Homologues: Orthologues: macaque U6 (83% identical), pig U6 (75% identical), rabbit U6 (65% identical), mouse Gm54605 (61% identical), rabbit U6 (58% identical). Paralogues in human: RNU6-1151P (80% identical), RNU6-348P (80% identical), RNU6-1075P (79% identical), RNU6-1243P (79% identical), RNU6-199P (79% identical), RNU6-29P (79% identical), RNU6-379P (79% identical), RNU6-41P (79% identical), RNU6-637P (79% identical), RNU6-797P (79% identical), RNU6-83P (79% identical), RNU6-1060P (78% identical), and 1281 more.